CCR7 (C-C motif chemokine receptor 7)
Diseases named in the same sentence as CCR7 in open-access papers (continued):
Sharing a sentence is not in itself a finding about the gene and the disease.
tumor (continued). "Like anti-CCR7 assets do, targeting cell adhesion exerts direct effects to the tumor cell (e.g. reduction of motility, invasiveness, and proliferation) that may impair homing to SLO." (PMID 34778050, 2021). "Strikingly, we found that a significant CXCR4 and CCR7 association was only detected in cells from the advanced primary tumours, whereas receptor interaction was practically absent in tumour cells from hyperplasia and early tumour stages." (PMID 34685420, 2021). "CCR7-positive staining was also detected in the tissue surrounding the tumours." (PMID 33761981, 2021). "The chemokine receptor CCR7 plays an important role in immune function and lymphoid trafficking and has been shown to be expressed in several malignant tumors with evidence for a role in tumor cell progression and clinical outcome." (PMID 34830848, 2021). "Likewise, immunosuppressive cells take advantage of CCR7 to locate themselves close to innate or adaptative anti-tumor immune cells, thus facilitating their tolerogenic or their inhibitory participation in the TME." (PMID 34778050, 2021). "In HEVhigh tumours compared with HEVlow tumours, gene profile of HEVs has shown upregulation of genes encoding lymphoid chemokines including chemokine (C-C motif) ligand (CCL) 19 (CCL19), CCL21, and CXCL13 as well as T-cell homing receptors (CCR7 and LSEL)." (PMID 33917287, 2021). "CCR7 expression has been observed in cHL-derived tumor cell lines and in primary tissue." (PMID 34778050, 2021). "CXCR4 and CCR7 are known to promote tumor metastasis via cell migration and invasion." (PMID 33406809, 2021). "Moreover, CCR7 also guides different accessory cell types that are needed to create and preserve pro-tumor niches and to protect cancer cells from spontaneous or drug-induced apoptosis." (PMID 34778050, 2021). "Confirming an inflammatory, anti-tumoral association, the proportion of M1-associated CCR7+ cells in the whole CD45+ immune cell population was shown to be correlated with low tumor volume and absence of extraprostatic extension." (PMID 34588590, 2021). "Tumor cells increase VEGF-C expression in response to the CCL21/CCR7 signal." (PMID 34160019, 2021). "Notably, increased CCR7 expression was correlated with tumor size, clinical stage, recurrence, lymph node metastasis, poor OS, and DFS of HNSCC." (PMID 33925575, 2021). "Therefore, additional comparative studies addressing biased signaling in both healthy and tumor tissues are mandatory to better understand the pathophysiological roles of these regulatory mechanisms in CCR7 and other CKRs." (PMID 34778050, 2021). "CCR7 (chemokine receptor 7) can inhibit angiogenesis according to the previous investigation, although available studies have shown that it fosters tumor progression." (PMID 33995379, 2021). "However, it was also reported that lymph node positive tumours showed more cytoplasmic CCR7 and that nuclear staining was exclusive to lymph node negative tumours." (PMID 34298676, 2021). "The CCL21/CCR7 axis has a dual role, since it can both regulate the homing of immune cells to the lymph node to prime and activate T cells, B cells, and dendritic cells and be involved in a metastatic tumor phenotype by promoting cancer cells migration." (PMID 34445452, 2021). "If such direct or indirect modulation of tumor-cell or milieu-derived CCR7-signaling stands out as a promising approach it is likely that in the coming years an extensive collection of novel evidence will help to better understand its biology and to refine CCR7-based translational applications." (PMID 34778050, 2021). "We observed multiple clusters of myeloid cells in NPC tumours, among which DC_C3_LAMP3 could be considered as a group of regulatory and tolerogenic DC, showing high expression of the migration (CCR7) and maturation (LAMP3) related genes." (PMID 33531485, 2021).
tumor (continued). "Furthermore, lymph node metastases from ACCs had significantly higher CCR7 H-scores compared to primary tumors, recurrences, or distant metastases, suggesting a possible role in lymphatic spreading of tumor cells." (PMID 34830848, 2021). "However, lymph node invasion is usually the first step in the metastatic process, where CCR7-expressing tumour cells are attracted to its ligand CCL21 that is abundantly expressed in the lymph nodes." (PMID 34298676, 2021). "Alternatively, tumor antigen could be added for uptake and cross-presentation very early during the expansion, and cells be administered while they still express CCR7 on the surface, however, in that case much fewer cells." (PMID 34149689, 2021). "In some of the tissue samples, F4/80- and CCR7-positive staining was observed within the tumours." (PMID 33761981, 2021). "Although it remains undetermined whether CCR7 agonists or antagonists should be used for anti-tumor activity, it is well established that the agonistic CCR7 activity of immune cells could yield a purposeful tool for increased antitumor immune activity." (PMID 34361107, 2021). "CCR7 is necessary for the migration of tumor-infiltrating DCs into tumor-draining lymph nodes." (PMID 34659209, 2021). "We hypothesized that a higher efficacy at reducing LN tumor burden would be achieved by a neutralizing anti-CCR7 monoclonal antibody (mAb) able to immobilize cancer cells and to elicit cell killing." (PMID 33841445, 2021). "CCR7 can also recruit regulatory cells that hamper anti-tumor immunity." (PMID 34778050, 2021). "Remarkably, stroma in oral squamous cell carcinomas has lymphoid properties characterized by abundant FRCs expressing extracellular matrix components of lymph nodes including tenascin-C and utilizing CCR7/CCL21 signaling for retaining CD11c+ immune cells in the tumor matrix tracks." (PMID 33912190, 2021). "The expression of CCR7 in tumour infiltrating CD8+ T cells may lead to a tumour‐specific immune response with potential antitumour activity, leading to a favourable prognosis for metastatic CRC patients." (PMID 33719152, 2021). "In addition, the caerin gel treatment recruits almost two-fold more activated CD8+ T cells to the TME, relative to the untreated tumour, which shows a synergistic effect derived from the regulation of S1pr1, Ccr7, Ms4a4b and Gimap family expression." (PMID 34858827, 2021). "BCP also suppressed the number of lipid vacuoles and F4/80+ macrophage (MΦ) and macrophage mannose receptor (MMR)+ M2-MΦs in tumor tissues and adipose tissues surrounding the lymph nodes and reduced the CCL19 and CCL21 levels in the lymph node and CCR7 expression in the tumor." (PMID 32998300, 2020). "Further, delivery of RNA coding for the lymphoid homing receptor CCR7 might potentially restore the migration ability of cDCs, which in principle can be suppressed by the local tumor microenvironment." (PMID 32674488, 2020). "CCR7 has been well-documented to comprehensively promote tumor development in many cancer types." (PMID 31991604, 2020). "Moreover, we detected that the generally higher frequency of protecting CCR7+ cells in healthy subjects decreased with age, yet still being higher than in tumor patients." (PMID 32082401, 2020). "Additionally, the production of CCL21 by the HEV endothelial cells recruits naïve CCR7+ T cells to tumor sites, which are essential in the generation of anti-tumor immunity." (PMID 32499782, 2020). "Interestingly, the swelling of dCLNs was weakened after anti-CCL21 or anti-CCR7 treatment in tumor-bearing mice." (PMID 32094452, 2020). "Positive CXCR4 expression was found in 195 (79.9%) samples of tumor tissues and 12 (4.9%) samples of normal tissues, while positive cases for CXCR5 and CCR7 were 155 (63.5%) and 117 (48.0%) samples of tumor tissues and 15 (6.1%) and six (2.5%) samples of normal tissues, respectively." (PMID 32896997, 2020).
tumor (continued). "The chemokine receptor CCR7 directs DC trafficking to LNs27 and we observed increased CCR7 expression on all three tumor-resident MHC-II+CD11c+ DC populations after m1928z-CD40L CAR T cell treatment: CD11b−CD103− DNs, CD11b−CD103+ cDC1s, and CD11b+CD103− cDC2s." (PMID 33268774, 2020). "CXCR5 and CCR7 expression were found on the membrane and in the cytoplasm of tumor cells." (PMID 32896997, 2020). "In addition, adipocytes increase C–C motif chemokine ligand 19 (CCL19) and CCL21 expression in LECs and C–C chemokine receptor type 7 (CCR7) expression in tumor cells, which attracts more tumor cells to the lymphatic vessels." (PMID 33203856, 2020). "In addition, the specific binding of CCL21 to C-C chemokine receptor type 7 (CCR7) expressed on the surface of tumor cells can promote lymph node metastasis of tumor cells." (PMID 33240857, 2020). "Moreover, CCR7 activation has been demonstrated to mediate the carcinogenesis and progression of tumor." (PMID 33158173, 2020). "FcγR engagement of immune complexes (ICs) by DCs induces their CCR-7 dependent migration to LNs, and we have shown that the combination of DC adjuvants with tumor-bound allogeneic antibody ICs induce robust anti-tumor T cell responses." (PMID 32657757, 2020). "Elevated expression levels of CXCR4, CXCR5 and CCR7 were found in tumor tissues (P < 0.001)." (PMID 32896997, 2020). "Furthermore, oxysterols have an indirect effect on DC migration through downregulating CCR7 expression, interfering with DC migration to the lymph nodes and so inhibiting DC-mediated antigen presentation and the induction of anti-tumour T cell responses." (PMID 32998240, 2020). "CCR7 also induces tumor angiogenesis by promoting VEGF-C expression in prostate cancer." (PMID 31991604, 2020). "Analysis of the total thymic cell population suggests insignificant changes in CCL17 (ligand for CCR4) and a modest decrease in CCL19 (ligands for CCR7) at day 25 but a drastic reduction in expression of CCL21 (ligands for CCR7) when comparing thymi harvested from tumor-bearing vs. control mice." (PMID 32582141, 2020). "In our study, we provide evidence that a reduction in both the CCR7 expression and the ability of DCs to migrate towards the draining lymph nodes may be triggered by the tumor acidic environment." (PMID 32438640, 2020). "The results of our study suggest that CCR7 mediates the migration of tumor cells may be through the “CCR7–AP1–MMP9” pathway." (PMID 30781353, 2019). "On the contrary, CCR7 showed a higher expression in tumor samples at the protein level." (PMID 31555130, 2019). "CCR7 is overexpressed by many tumors driving both tumor growth and metastatization." (PMID 30894861, 2019). "The mRNA levels of Ccr7, Mmp9, c-Fos (Fos proto-oncogene, AP-1 transcription factor subunit), c-Jun (Jun), Ccl19 (C-C motif Chemokine Ligand 19) and Ccl21 were significantly reduced in tumor of CRE treated mice." (PMID 30781353, 2019). "Importantly, anti-CD19-CAR and CCR7 conferred to NK cells an up to 5 fold increase in killing of CD19+ tumor cells and a 6 fold increase of migratory capability in response to CCL19 or CCL21, respectively." (PMID 31114587, 2019). "Since tumor antigen trafficking to the draining lymph nodes is crucial for the anticancer DC vaccine, we carried out detailed studies on the migration of DCs and expression of CCR7." (PMID 29632307, 2018). "We further investigated the role of CCR7 on CCL19-related tumor angiogenesis." (PMID 30250188, 2018). "Interestingly, upon ICAM-1 blockade, the expression of the chemotactic receptor CCR7 augments in tumor infiltrating lymphocytes and in in-vitro de-clustered T cells, as well as their ability to transmigrate across lymphatic endothelial cells." (PMID 30258446, 2018). "Hence, CCR7 play crucial role in lymphatic migration of tumour cells similarly to lymph nodes draining dendritic cell immigration." (PMID 30417146, 2018).
tumor (continued). "In solid tumors CCR7 acquisition by NK cells may depend on close cell-to-cell contacts with macrophages or dendritic cells, whereas it is less plausible that tumor cells could play a relevant role." (PMID 30364222, 2018). "Recent articles have indicated that the CCL19/CCR7 axis can promote tumor progression." (PMID 30250188, 2018). "It has been reported that invasive breast cancer cells may undergo targeted migration towards lymphatics induced by tumour cell expression of CCR7 bound to its ligands called the lymphoid homing chemokines CCL19/CCL21." (PMID 30417146, 2018). "Lymph endothelial cells secrete chemokines including chemokine (C-X-C motif) ligand 12 (CXCL12) and chemokine (C-C motif) ligand 21 (CCL21) to recruit tumor cells that express chemokine (C-C motif) receptor 7 (CCR7) and chemokine (C-X-C motif) receptor 4 (CXCR4)." (PMID 29805773, 2018). "Similar to CCR7 being useful for the movement of T cells within lymph nodes, when chemokine receptors are expressed in tumor cells, they may direct organ-targeted tumor metastasis." (PMID 30004409, 2018). "Since CCL21 was found to interact with PDPN the regulation of both molecules may control the entry of CCR7+NK cells and their cytotoxicity in the tumor." (PMID 28416768, 2017). "However, in recent years, aberrant high CCR7 expression has also been identified on several tumor types, linking to a potential invasive phenotype." (PMID 28114889, 2017). "Together, these data suggest CCR7 cells have lower short-term direct cytotoxicity to target tumour cells, which we and others propose is indicative of an early-differentiated phenotype and increased capacity of long term engraftment in vivo, a trait required for tumour eradication." (PMID 28239467, 2017). "Despite this we analysed whether CCR7+ had more anti-tumour potency than CCR7- magnetically sorted DMF5 TCR transduced T cells over the course of 3 weeks in NSG subcutaneously inoculated with Mel624 tumours." (PMID 28239467, 2017). "The chemokine receptor CCR7 contributes to various physiological and pathological processes including T cell maturation, T cell migration from the blood into secondary lymphoid tissues, and tumor cell metastasis to lymph nodes." (PMID 28819198, 2017). "Furthermore, it was shown that C-C motif chemokine receptor 7 (CCR7) is required for CD 103+ DCs to traffic tumor antigens to the LN and that CCR7 levels correlate with T cell infiltrate and patient survival." (PMID 29050360, 2017). "CCR7+ carcinoma cells, as they are less retained in the primary tumor site, might thus be attracted to CCL21+ sites such as peripheral lymph nodes, where the chemokine is presented on endothelial cells as shown in this work." (PMID 28416768, 2017). "Moreover, LCs migrated to the skin draining lymph (LNs) in a CCR-7 dependent manner that leads to an increase in tumor infiltrating T regulatory cells and resistance to radiotherapy." (PMID 28157211, 2017). "Next, we also detected the role of CCR7 in CCL19‐induced tumor migration and invasion." (PMID 28378417, 2017). "Thus, here through immunohistochemistry (IHC), we retrospectively evaluated the CCR7 expression in 110 primary tumor specimens of mRCC patients treated with sunitinib and sorafenib." (PMID 28114889, 2017). "It has been suggested that CCR7 positive tumor cells could mimic the normal lymphocyte homing function and interact with lymph vessels, leading to subsequent lymph node specific metastasis." (PMID 28114889, 2017). "Antagonists towards CCR7 are capable of reducing stem-like cell content and activity, and γ-secretase inhibitors and antibodies that block the Notch pathway have also been shown to specifically target tumor-initiating cells." (PMID 28137279, 2017). "Indeed, we observed a slight upregulation of both CCR7 and CXCR4, essential receptors required for LN trafficking of DCs, upon loss of MK2 in tumour-infiltrating DCs." (PMID 28924177, 2017).
tumor (continued). "Moreover, as with CD34 mRNA-electroporated NK cells, NK cells electroporated with CCR7 mRNA maintained potent cytotoxicity function against tumor cells." (PMID 27047492, 2016). "CCR7 is involved in the migration of dendritic cells to draining lymph nodes, thus suppression of this chemokine receptor results in trapping of dendritic cells in the tumour and subsequent interference with antigen presentation to anti-tumour T-cells." (PMID 27341022, 2016). "Moreover, immunohistochemical analysis and tumor cell-specific CCR7 staining revealed significantly reduced lung and liver metastases in lithium-treated mice, compared with control mice." (PMID 26857144, 2016). "Before loading with tumour lysate, DCs were characterized by flow cytometry to analyse the expression of MHC class I and II molecules, costimulatory molecules (CD86, CD80, CD40), and markers associated with maturation (CD83, CCR7, PD-L1)." (PMID 26795765, 2016). "In this context, CCR7 acquired by NK cells via trogocytosis has been shown to enhance their lymph node homing upon adoptive transfer to athymic nude mice, contributing to eliminate lymph node tumor metastases." (PMID 27774094, 2016). "Finally, we used immunohistochemistry to compare CCR7-high and CCR7-low tumor samples from GC patients along with 20 samples of healthy gastric tissue, which served as a control." (PMID 26176983, 2015). "Knockdown of TAB1 attenuated CCR7 expression and tumor growth in an orthotopic animal study." (PMID 25557171, 2015). "We next investigated whether inhibition of the TAB1/TAK1 signaling (which reduced CCR7 expression) affects tumor metastasis." (PMID 25557171, 2015). "Moreover, TGF-β1 stimulation significantly (P < 0.01) increased the invasiveness of both tumor cell lines, and the effect was completely blocked by neu-CCR7, a neutralizing antibody, (P < 0.01)." (PMID 26176983, 2015). "Interestingly, some tumor cells express the CCL21 receptor CCR7, thereby enabling them to access lymphatic vessels." (PMID 25254213, 2014). "This CCR7/JAK2/STAT3 signal pathway regulates tumor metastasis by E-cadherin-mediated tumor EMT." (PMID 25405202, 2014). "Moreover, Ccr7 has been reported as a mediator of progression and homing to lymph nodes in multiple tumour types, and to stimulate survival pathways by autocrine or paracrine mechanisms." (PMID 24586197, 2014). "Moreover, CCR7 signaling is considered to mediate both angiogenesis and tumor metastasis in different tumor microenvironments." (PMID 25260647, 2014). "CCR7 promotes tumor growth and metastasis in response to endogenous SLC or ELC." (PMID 24040244, 2013). "CCR7 is expressed not only in naive T cells and DCs, but also in some tumor cells." (PMID 24040244, 2013). "The delay in the tumor growth exerted by the anti-human CCR7 mAb might involve the death of tumor cells by cytotoxicity." (PMID 24305507, 2013). "The anti-CCR7 mAb exerts a potent anti-tumor activity and might represent an interesting therapeutic alternative to conventional therapies." (PMID 24305507, 2013). "Moreover, an increased number of apoptotic tumor cells was detected in mice treated with the anti-CCR7 mAb compared to the untreated animals." (PMID 24305507, 2013). "CCR7 expression in tumor cells is closely correlated with their metastasis and malignancy." (PMID 24040244, 2013). "CCR7 expression in some tumor cells even can be used as molecular markers to determine whether the tumors are metastatic." (PMID 24040244, 2013). "Moreover, while some chemokine receptors, such as CXCR4 and CCR7, have been extensively studied, additional studies are needed to examine the role of other chemokines in tumor progression and metastasis." (PMID 24259307, 2013). "In the context of cancer CCR7 expression of tumor cells has been associated with lymph node metastasis of various tumors, including breast (for review see:)." (PMID 23667660, 2013).